KRT6C (keratin 6C)
Description:
Structural component of intermediate filaments in epithelial keratinocytes. Forms heteropolymers with the type I keratins, likely including KRT16 and KRT17, assembling keratin intermediate filament networks that contributes to the structural framework and mechanical resilience of stratified epithelia, particularly in palmoplantar epidermis.
Synonyms: KRT6E; K6E; PPKNEFD
Tractability: PROTAC: ubiquitination databases record sites on it.
Gene: Protein-coding gene on chromosome 12 (52,468,516 to 52,473,805, reverse strand). Ensembl gene ENSG00000170465.
Subcellular location (Human Protein Atlas): Intermediate filaments
Pathways (Reactome):
Developmental Biology: Formation of the cornified envelope; Keratinization
Gene Ontology:
Molecular function: protein binding; structural constituent of skin epidermis
Biological process: intermediate filament cytoskeleton organization; intermediate filament organization; keratinization
Cellular component: extracellular exosome; cytosol; intermediate filament; keratin filament
Genetic constraint (gnomAD): Loss-of-function variants: 46 observed, 43.88 expected, observed/expected ratio (o/e) 1.05, 90% interval 0.83 to 1.34. The upper end of that interval is the gene's LOEUF score, 1.34, which puts it in group 5 of 6, group 1 being the genes least tolerant of losing a copy. Missense variants: 526 observed, 610.06 expected, observed/expected ratio (o/e) 0.86, 90% interval 0.8 to 0.93. Synonymous variants: 222 observed, 236.35 expected, observed/expected ratio (o/e) 0.94, 90% interval 0.84 to 1.05.
Homologues: Orthologues: mouse Krt6a (86% identical), mouse Krt6b (84% identical), rat LOC100365213 (83% identical), rat LOC120093742 (83% identical), chimpanzee KRT6C (83% identical), rat Krt6c (82% identical), rat LOC102553726 (80% identical), mouse Gm5414 (70% identical), rat AABR07001416.1 (69% identical). Paralogues in human: KRT6B (99% identical), KRT6A (98% identical), KRT5 (79% identical), KRT75 (71% identical), KRT3 (66% identical), KRT76 (65% identical), KRT1 (64% identical), KRT2 (62% identical), KRT79 (61% identical), KRT4 (59% identical), KRT77 (55% identical), KRT73 (55% identical), and 56 more.
Diseases named in the same sentence as KRT6C in open-access papers:
KRT6C is named in the same sentence as 34 diseases in open-access papers, as found by Europe PMC text mining. Sharing a sentence is not in itself a finding about the gene and the disease. The quoted sentences say what the papers report.
lung adenocarcinoma (3 papers, 2019 to 2022). A carcinoma that arises from the lung and is characterized by the presence of malignant glandular epithelial cells. "High expression of keratin 6C is associated with poor prognosis and accelerates cancer proliferation and migration by modulating epithelial-mesenchymal transition in lung adenocarcinoma." (PMID 36072430, 2022).
breast carcinoma (2 papers, 2024 to 2025). "Transcriptomic analysis revealed upregulation of macrophage activation markers, genes such as S100A8, S100A2, KRT81, KRT6C, MARCO and MMP1, as well as processes related to keratinization and the formation of a cornified envelope in breast cancer cells." (PMID 41073799, 2025). "Similar to our results, the in silico breast cancer studies found reduced KRT6B and KRT6C levels in the tumor tissues, compared to the cancer-free samples." (PMID 39000463, 2024).
Palmoplantar keratoderma (2 papers, 2018 to 2021). Abnormal thickening of the skin of the palms of the hands and the soles of the feet. "In humans, the KRT6 family includes a third member (KRT6C, encoding K6c), mutations in which have been associated with a milder form of PC with no/minor nail defects (PC-K6c) that was initially reported as palmoplantar keratoderma, non-epidermolytic, focal or diffuse (PPKNEFD, OMIM #615735)." (PMID 29357356, 2018).
psoriasis (2 papers, 2022). An autoimmune condition characterized by red, well-delineated plaques with silvery scales that are usually on the extensor surfaces and scalp. "A series of psoriasis-related genes, such as S100A8, S100A9, KRT6A (keratin 6A), KRT6B, KRT6C, KRT16, and MMP9 (metalloproteinase 9), were also down-regulated." (PMID 35273606, 2022). "Further psoriasis and AD share the KRT6A, KRT6B, KRT6C, KRT16, KRT17 as their common DEGs." (PMID 35874668, 2022).
squamous cell carcinoma (2 papers, 2022 to 2024). A carcinoma arising from squamous epithelial cells. "By validating the expression profiles of six specific genes (MIR205HG, KRT5, KRT6A, KRT6C, SERPINB5, and DSG3), selected based on a previously established 53-gene signature, we consistently observed higher expression levels in squamous cell carcinoma (SCC) compared to adenocarcinoma (ADC)." (PMID 38612418, 2024).
colorectal cancer (1 paper, 2024). A primary or metastatic malignant neoplasm that affects the colon or rectum. "Existing research indicates that circ-KRT6C is overexpressed in colorectal cancer tissues and cells, and it is associated with overall patient survival." (PMID 38612418, 2024). "In colorectal cancer, silencing circ-KRT6C has been shown to inhibit growth, migration, invasion, and immune evasion while promoting apoptosis in cancer cells, particularly when miR-485-3p is deficient." (PMID 38612418, 2024). "Circ-KRT6C has been found to increase PDL1 expression by acting as a “sponge” for miR-485-3p, thereby enhancing the malignancy of colorectal cancer cells." (PMID 38612418, 2024).
head and neck cancer (1 paper, 2021). A primary or metastatic malignant neoplasm affecting the head and neck. "The Cancer Genome Atlas (TCGA) also reports high RNA expression of KRT6C in head and neck cancer." (PMID 33564003, 2021).
head and neck squamous cell carcinoma (1 paper, 2024). A squamous cell carcinoma that arises from any of the following anatomic sites: lip and oral cavity, nasal cavity, paranasal sinuses, pharynx, larynx, and salivary glands. "The aim of this study was to evaluate type II cytokeratins (KRT): KRT6A, KRT6B, and KRT6C protein concentrations in 54 tumor and margin samples of head and neck squamous cell carcinoma (HNSCC)." (PMID 39000463, 2024).
inflammatory skin disease (1 paper, 2023). Inflammatory skin disorders covers a broad category that includes many conditions ranging in severity, from mild itching to grave medical health complications These disorders are common in people of all ages and races. "The spinous cluster also expressed KRT6A, KRT6C, and KRT16, which have been associated with inflammatory skin diseases and barrier dysfunction." (PMID 37675143, 2023).
keratosis pilaris (1 paper, 2024). A form of dry skin characterized by hair follicles plugged by scale. "Proteomic profiling revealed heightened expression of KRT6C and FABP5 in arsenic-induced keratosis pilaris." (PMID 38596682, 2024).
ovarian carcinoma (1 paper, 2017). A malignant neoplasm originating from the surface ovarian epithelium. "KRT5 and KRT6 (KRT6A, KRT6B & KRT6C) gene expression was assessed in publically available serous ovarian cancer data sets, ovarian cancer cell lines and primary serous ovarian cancer cells." (PMID 28147318, 2017). "KRT6C was expressed by all ovarian cancer cell lines as well as LP-9 cells." (PMID 28147318, 2017).
pachyonychia congenita (1 paper, 2025). Pachyonychia congenita (PC) is a rare genodermatosis predominantly featuring painful palmoplantar keratoderma, thickened nails, cysts and whitish oral mucosa. "Pachyonychia congenita (PC) is a rare hereditary condition affecting keratinization, which results from an underlying genetic mutation in one of the five keratin genes: KRT6A, KRT6B, KRT6C, KRT16, or KRT17." (PMID 40686559, 2025).
pancreatic cancer (1 paper, 2023). "Interestingly, KRT6C was extremely highly expressed in WT pancreatic cancer cells BxPC-3 (p < 0.01)." (PMID 38268915, 2023). "Indeed, there are extremely few high-quality mechanistic studies on other signature genes (e.g., CSTF2, APOM, and KRT6C) that may serve as targets for subsequent studies on the molecular mechanisms of pancreatic cancer." (PMID 38268915, 2023). "The mRNA expression levels of CSTF2, FAF2, KIF20B, AKR1A1, APOM, KRT6C, and CD70, which were included in the prognostic model, were detected in different types of pancreatic cancer cell lines." (PMID 38268915, 2023).
serous ovarian cancer (1 paper, 2017). "Furthermore, KRT5 and KRT6C mRNA expression was assessed in chemotherapy sensitive and chemotherapy resistant primary serous ovarian cancer cells derived from patient ascites." (PMID 28147318, 2017). "KRT5 but not KRT6C mRNA expression was increased in chemotherapy resistant primary serous ovarian cancer cells compared to chemotherapy sensitive cells." (PMID 28147318, 2017).
triple-negative breast carcinoma (1 paper, 2012). An invasive breast carcinoma which is negative for expression of estrogen receptor (ER), progesterone receptor (PR), and human epidermal growth factor receptor 2 (HER2). "Several basal-related genes directly corresponding to expression levels of cytokeratins and EGFR protein marker, including KRT5, KRT6C, KRT6E, KRT14, and EGFR genes, were found to be extensively up-regulated in triple-negative breast cancer." (PMID 23049873, 2012).
cancer (11 papers, 2011 to 2025). A tumor composed of atypical neoplastic, often pleomorphic cells that invade other tissues. "Expression of KRT6C is associated with abnormal differentiation or enhanced proliferation, like in case of wound healing or cancer with exception of only a few body sites." (PMID 33564003, 2021). "Additionally, circ-KRT6C inhibition suppresses tumor growth in vivo, suggesting it plays a significant role in immune evasion and cancer progression." (PMID 40739089, 2025). "However, KRT6C is less studied in cancer, and its specific mechanism is still unclear." (PMID 37007021, 2023). "PML, C3, TXN, KRT6C, F2, PTK2, TNF, which could enable HIF-mediated inflammatory response during cancer development." (PMID 36845724, 2023).
tumor (6 papers, 2021 to 2025). "We showed an association between the KRT6C protein level and clinical parameters T and N in tumor and margin samples." (PMID 39000463, 2024). "In a study evaluating the salivary proteins as potential biomarkers for the early diagnosis of OSCC, it was reported that KRT6C was significantly elevated at the tumor stage T3/T4, compared to T1/T2, whereas in our study we did not note any differences." (PMID 39000463, 2024). "Our study showed that the median protein concentrations of KRT6B and KRT6C were higher in HPV(+) patients than in the group of HPV(−) in tumor tissues." (PMID 39000463, 2024). "KRT6C protein from the margin samples was significantly mildly correlating with all three KRT6 proteins in the tumor samples." (PMID 39000463, 2024). "Moreover, we found a similar correlation in the case of p16 status, where we obtained higher levels of KRT6B and KRT6C proteins in p16-positive tumor samples." (PMID 39000463, 2024). "Due to the role of KRT6 proteins in cell growth, invasion, and migration processes, it is hypothesized that the levels of KRT6A, KRT6B, and KRT6C will be changed in tumor samples compared to margin samples in patients with HNSCC." (PMID 39000463, 2024). "The increased levels of KRT6B and KRT6C proteins in the tumor margin observed in our study might therefore indicate that these proteins may affect the immune response and the immune microenvironment." (PMID 39000463, 2024). "After tumor mutation profile and copy number variation (CNV) analyses, we established and validated a prediction model of KRAS mutations, based on survival analysis and mRNA expression, that contained seven genes: CSTF2, FAF2, KIF20B, AKR1A1, APOM, KRT6C, and CD70." (PMID 38268915, 2023). "Therefore, we suggested that the upregulation of KRT6B and KRT6C protein levels in the tumor and margin samples of regular alcohol drinkers, compared to occasional drinkers, could be related to increased keratinization, in response to the tissue damage caused by alcohol and its metabolites." (PMID 39000463, 2024). "Conversely, KRT6C expression in tumor tissues declined as compared to normal tissues without significant difference (p > 0.05)." (PMID 40156045, 2025). "Compared to that of the paired normal tissues, the mRNA expression levels of KRT6A and KRT6B, but not that of KRT6C, were significantly increased in the paired tumor tissues." (PMID 38398015, 2024).
KRT6C also shares sentences with these, for which no sentence is quoted: adenocarcinoma (2 papers); lung squamous cell carcinoma (2); bladder tumors (1); epidermolytic hyperkeratosis (1); Fibroadenoma (1); hepatocellular carcinoma (1); Hyperkeratosis (1); lung carcinoma (1); melanoma (1); metastatic melanoma (1); Nail dystrophy (1); nonepidermolytic palmoplantar keratoderma (1); oral cancer (1); oral squamous cell carcinoma (1); plantar wart (1); urothelial cell carcinomas (1); White sponge nevus (1).